METTL1 (methyltransferase 1, tRNA methylguanosine)
Diseases named in the same sentence as METTL1 in open-access papers (continued):
Sharing a sentence is not in itself a finding about the gene and the disease.
gastric cancer (8 papers, 2019 to 2025). A primary or metastatic malignant neoplasm involving the stomach. "Recent research has indicated that higher METTL1 expression is associated with improved patient survival compared to lower expression in gastric cancer patients." (PMID 40809384, 2025). "High METTL1 expression was found to correlate with improved survival rates in gastric cancer patients (P = 0.042), and the random forest model, based on METTL1 and associated prognostic genes, achieved a significant predictive performance (AUC = 0.863)." (PMID 38693422, 2024). "This study underscores the potential of METTL1 as a biomarker in enhancing the efficacy of gastric cancer immunotherapy." (PMID 38693422, 2024). "Experiments in vitro and in vivo demonstrated that METTL1 enhances gastric cancer cell activity by suppressing T cell proliferation and upregulating CTLA4 and PDCD1." (PMID 38693422, 2024). "Experimental manipulation revealed that downregulation of METTL1 expression curtails the proliferation of gastric cancer cells while concurrently elevating apoptotic rates." (PMID 38693422, 2024). "Conversely, the forced overexpression of METTL1 augments cell proliferation, underscoring its central role in the modulation of gastric cancer cell behavior." (PMID 38693422, 2024). "We conducted a co-culture experiment of AGS cells with T cells to investigate and confirm the regulatory mechanism of METTL1 on gastric cancer cells." (PMID 38693422, 2024). "To further validate the findings of the bioinformatics analysis regarding the regulation of gastric cancer immunotherapy by the METTL1 gene, we performed supplementary in vitro cell experiments for verification." (PMID 38693422, 2024). "Further exploration into the regulatory dynamics of METTL1 has underscored its pivotal importance in gastric cancer pathophysiology." (PMID 38693422, 2024). "Furthermore, we observed an overexpression of METTL1 in gastric cancer tissue samples obtained from 69 patients with gastric cancer." (PMID 38693422, 2024). "Additionally, experimental studies aimed at elucidating the mechanistic role of METTL1 in gastric cancer progression and response to therapy are warranted." (PMID 38693422, 2024). "In gastric cancer, Tspan31 was found to be upregulated in tumor tissues, and silencing Tspan31 effectively inhibited migration and proliferation of GC cells by impairing the METTL1/CCT2 pathway." (PMID 38389703, 2024). "Conversely, the overexpression of METTL1 decreased the apoptosis rate of gastric cancer cells." (PMID 38693422, 2024). "The implications of our findings are profound, indicating that targeting METTL1 and its downstream signaling pathways could represent a viable strategy for the treatment of gastric cancer." (PMID 38693422, 2024). "The upregulation of the METTL1 gene within tumor specimens correlates with improved patient survival outcomes, suggesting that METTL1 may influence both the initiation and progression of gastric cancer." (PMID 38693422, 2024). "Besides, miR-149-3p was the downstream target of METTL1, and overexpression of miR-149-3p decreased chemoresistance of multiple cancers to cisplatin, such as ovarian cancer, esophageal cancer, gastric cancer and non-small cell lung cancer." (PMID 31866582, 2019). "We initially detected the expression levels of METTL1 in human gastric mucosal epithelial cells (GES-1) and gastric cancer cell lines (AGS, MKN45, and SNU-216) using RT-qPCR." (PMID 38693422, 2024). "METTL1 is an RBP, and the expression of METTL1 in gastric cancer is higher than that in normal tissues." (PMID 39850560, 2024). "A study on gastric cancer showed that overexpression of METTL1 promoted CTLA-4 and PD-1 expression, suggesting that METTL1 may facilitate immune evasion by enhancing the expression of these inhibitory checkpoints." (PMID 40809384, 2025).
lung adenocarcinoma (7 papers, 2021 to 2025). A carcinoma that arises from the lung and is characterized by the presence of malignant glandular epithelial cells. "METTL1, METTL3, METTL4, METTL5, METTL6 and METTL13 were associated with poor prognosis in various tumors including liver hepatocellular carcinoma (LIHC), breast invasive carcinoma (BRCA), and lung adenocarcinoma (LUAD)." (PMID 41194259, 2025). "Moreover, in lung adenocarcinoma cell lines, a positive feedback loop has been suggested, in which METTL1 expression enhances the AKT-mTOR signalling pathway." (PMID 37516825, 2023).
colorectal cancer (6 papers, 2019 to 2025). A primary or metastatic malignant neoplasm that affects the colon or rectum. "Our data uncover that METTL1 plays an important supportive role in colorectal cancer proliferation and progression, providing a potential therapeutic target for colorectal cancer." (PMID 37692515, 2024). "The result showed that METTL1 expression was up-regulated in colorectal cancer tissues compared to matched adjacent normal intestinal epithelial tissues." (PMID 37692515, 2024). "Here, we found that the expression of the member of methyltransferase-like (METTL) family-METTL1, the m7G “writers”, was remarkably up-regulated in colorectal cancer tissue and positively correlated with poor prognosis." (PMID 37692515, 2024). "Kaplan–Meier analysis showed that the elevated METTL1 expression was significantly positively correlated with shortened overall survival of colorectal cancer patients (P = 0.017)." (PMID 37692515, 2024). "The results indicated that METTL1 was remarkably up-regulated in colorectal cancer tissues compared with normal tissues." (PMID 37692515, 2024). "We extended these analyses to an unrelated colorectal cancer cell line (Caco-2 cells), which expresses METTL1 at levels comparable to those observed in A549 cells." (PMID 31031083, 2019). "METTL1 mediates m7G methylation of PKM mRNA and enhances the expression of its encoded PKM2, while increased PKM2 dimer expression and nuclear translocation activated CD155 expression and induced colorectal cancer immune evasion." (PMID 40443650, 2025). "METTL1 knockdown suppressed colorectal cancer cell growth and G1/S phase transition." (PMID 37692515, 2024). "As an important regulator of m7G, METTL1 functions as a tumor suppressor in colorectal cancer." (PMID 35614935, 2022).
esophageal cancer (5 papers, 2019 to 2025). A primary or metastatic malignant neoplasm involving the esophagus. "In esophageal cancer, NSUN5 is associated with METTL1 and positively regulates its expression, where NSUN5 directly binds to the METTL1 transcript, promoting its m5C modification in esophageal cancer cells." (PMID 41462962, 2025). "For example, we found that METTL1 was significantly overexpressed in LUAD, lung squamous cell carcinoma (LUSC), esophageal carcinoma (ESCA), and colorectal adenocarcinoma (COADREAD) samples compared to normal samples." (PMID 34285249, 2021). "Especially, METTL1 and WDR4 showed dramatic upregulation in Esophageal Carcinoma (TCGA-ESCA)." (PMID 35304469, 2022).
adrenocortical carcinoma (4 papers, 2021 to 2025). "It was found that the lower infiltrating levels of CD8+ T cells was found in clinical adrenocortical carcinoma samples with high METTL1 expression." (PMID 40443650, 2025). "The results obtained using Cox regression analyses are represented as forest maps, which showed a significant relationship between METTL1 expression and prognosis and survival of patients with adrenocortical carcinoma, KIRC, LGG, LIHC, and mesothelioma." (PMID 34838021, 2021).
cardiac hypertrophy (4 papers, 2024 to 2026). "Deficiency of METTL1 attenuates cardiac hypertrophy and dysfunction upon pressure overload from transverse aortic constriction or angiotensin II stimulation, whereas cardiac‐specific overexpression of METTL1 drives cardiac remodelling." (PMID 39979979, 2025). "YY1 has been reported to act as a transcriptional factor, activating METTL1 expression during cardiac hypertrophy." (PMID 39979979, 2025). "Mettl1 knockout alleviates cardiac hypertrophy and dysfunction upon pressure overload from TAC or Ang II stimulation." (PMID 38810124, 2024). "We further demonstrated that this upregulation of Mettl1 is a critical driver of cardiac hypertrophy and remodeling during pressure overload, providing a novel insight into the crucial role of Mettl1 in the context of cardiac pathology." (PMID 38810124, 2024). "To investigate the functional role of Mettl1 in cardiac hypertrophy, we generated whole‐body Mettl1 knockout mice." (PMID 38810124, 2024). "Supporting this notion, our data demonstrate that SRSF9 acts as a pro‐hypertrophy protein, and knockdown of SRSF9 rescues TAC or Mettl1‐induced cardiac hypertrophy and remodeling." (PMID 38810124, 2024). "This study characterized the critical role and elucidated the molecular mechanism of Mettl1‐mediated m7G modification in cardiac hypertrophy and heart failure in the context of pressure overload." (PMID 38810124, 2024). "Cardiac hypertrophy was also evident in Mettl1‐overexpressing mice, as evidenced by a marked increase in LVPW;d, HW/TL, and CSA." (PMID 38810124, 2024). "Together, these findings indicate that YY1 acts as an upstream regulator to activate Mettl1 expression during cardiac hypertrophy." (PMID 38810124, 2024). "In this study, we aimed to investigate the role and mechanism of Mettl1‐mediated m7G RNA modification in cardiac hypertrophy." (PMID 38810124, 2024). "Our study uncovers a previously unrecognized role of Mettl1 as a central driver of cardiac hypertrophy and remodeling under pressure overload, as demonstrated through using gain‐and‐loss‐of‐function studies conducted in vivo and in vitro." (PMID 38810124, 2024). "The study identifies Mettl1 as a crucial regulator of cardiac hypertrophy, providing a novel therapeutic target for HF." (PMID 38810124, 2024). "Moreover, cardiac‐specific overexpression of ATPIF1 induced myocardial hypertrophy and inhibited the protective effect of silencing METTL1 on cardiac I/R injury." (PMID 41510184, 2026). "This study reveals that METTL1 plays an important role in driving cardiac hypertrophy by regulating the SRSF9/NFATc4 axis, suggesting that targeting METTL1 could be an efficient way to treat cardiac hypertrophy and HF." (PMID 39979979, 2025). "Second, in addition to SRSF9, we cannot exclude the possibility that other mRNAs or tRNAs may also serve as the potential targets of Mettl1 and contribute to cardiac hypertrophy." (PMID 38810124, 2024). "To investigate whether m7G methyltransferase Mettl1 is involved in cardiac hypertrophy, we assessed Mettl1 expression in the hearts of patients diagnosed with heart failure." (PMID 38810124, 2024). "To elucidate the mechanism by which Mettl1 drives cardiac hypertrophy, we employed RNA‐seq combined with m7G methylated RNA sequencing (m7G‐seq) for whole transcriptome profiling and m7G sites mapping in Mettl1‐overexpressing mouse myocardium and NMCMs, respectively." (PMID 38810124, 2024). "YY1 acts as a transcriptional factor for Mettl1 during cardiac hypertrophy." (PMID 38810124, 2024). "Further exploration of Mettl1 and its downstream effectors may provide valuable insights into the development of novel therapeutic interventions for cardiac hypertrophy and heart failure." (PMID 38810124, 2024). "Furthermore, Mettl1 KO mice exhibited less cardiac hypertrophy and reduced heart size, HW/TL, LW/TL, HW/BW, and cardiomyocytes CSA post‐Ang II relative to WT mice." (PMID 38810124, 2024).
cardiac hypertrophy (continued). "Furthermore, cardiac hypertrophy, as displayed by the increased CSA and hypertrophic gene expression caused by overexpression of Mettl1, was attenuated by silencing of SRSF9." (PMID 38810124, 2024). "This study elucidates a previously unknown role and the molecular mechanism by which Mettl1‐mediated m7G modification contributes to cardiac hypertrophy." (PMID 38810124, 2024). "In conclusion, our study elucidates a previously unknown role and the molecular mechanism by which Mettl1‐mediated m7G modification contributes to cardiac hypertrophy." (PMID 38810124, 2024). "Next, we investigated whether Mettl1‐induced cardiac hypertrophy is mediated by SRSF9." (PMID 38810124, 2024). "We demonstrate that Mettl1 enhances the stability of SRSF9 through m7G modification, leading to upregulation of NFACT4 expression and promotion of cardiac hypertrophy and heart failure progression." (PMID 38810124, 2024). "The findings indicate that Mettl1 enhances the stability of SRSF9 through m7G modification, resulting in the upregulation of NFACT4 expression and the promotion of cardiac hypertrophy and heart failure progression." (PMID 38810124, 2024). "To identify the specific target of Mettl1, we cross‐referenced the results of KEGG and GO analyses, resulting in 14 probable genes that may be involved in cardiac hypertrophy‐related pathways." (PMID 38810124, 2024). "Mechanically, Mettl1 increases SRSF9 expression by inducing m7G modification of SRSF9 mRNA, facilitating alternative splicing and stabilization of NFATc4, thereby promoting cardiac hypertrophy." (PMID 38810124, 2024).
cholangiocarcinoma (4 papers, 2021 to 2025). A carcinoma that arises from the intrahepatic biliary tree (intrahepatic cholangiocarcinoma) or from the junction, or adjacent to the junction, of the right and left hepatic ducts (hilar cholangiocarcinoma). "Upregulated METTL1 and WDR4 promoted the translation of oncogenic transcripts depending on m7G-modified tRNA to promote intrahepatic cholangiocarcinoma progression." (PMID 36396627, 2022).
heart failure (4 papers, 2024 to 2025). Inability of the heart to pump blood at an adequate rate to meet tissue metabolic requirements. "Specific knockout of METTL1 in fibroblasts has been shown to mitigate myocardial infarction-induced heart failure and myocardial fibrosis." (PMID 39155349, 2024). "Increased levels of RNA m7G modification mediated by METTL1 were observed in cardiac fibrosis tissue and TGF-β1-induced cardiac fibroblast proliferation, and knocking out METTL1 in fibroblasts alleviated heart failure and cardiac fibrosis induced by myocardial infarction." (PMID 39155349, 2024).
hepatoblastoma (4 papers, 2022 to 2024). Hepatoblastoma (HB) is a malignant hepatic tumor and is the most common pediatric liver cancer. "Overall, we demonstrated that three SNPs in the METTL1 gene synergistically confer increased hepatoblastoma susceptibility." (PMID 35986847, 2022). "In the present study, we identified METTL1 as a gene associated with hepatoblastoma susceptibility." (PMID 35986847, 2022). "In vitro and in vivo studies should be performed to demonstrate the involvement of METTL1 in hepatoblastoma development and/or progression in the future." (PMID 35986847, 2022). "Our group has previously reported that many genetic variants of genes encoding RNA m6A and m7G methyltransferase, demethylase, and m6A-reading proteins confer hepatoblastoma susceptibility, including METTL3, METTL4, AlkB homolog 5 (ALKBH5), FTO, YTHDC1, YTHDF1, WTAP, WDR4, and METTL1." (PMID 37531210, 2023). "In the future, the role of METTL1 should be investigated in the tumorigenesis of hepatoblastoma." (PMID 36186903, 2022). "To date, the impacts of METTL1 in hepatoblastoma remain unknown." (PMID 35986847, 2022). "However, whether METTL1 gene polymorphisms confer susceptibility to hepatoblastoma has not been reported." (PMID 35986847, 2022). "Finally, the major weakness of the study is the lack of biologically relevant evidence that METTL1 plays a role in hepatoblastoma pathogenesis." (PMID 35986847, 2022).
primordial dwarfism (4 papers, 2020 to 2025). "METTL1 is an m7G RNA methyltransferase, and mutations in the human m7G methyltransferase complex METTL1/WDR4 can lead to primordial dwarfism and brain malformation." (PMID 32698871, 2020). "WDR4 functions as a scaffold for METTL1 and tRNA binding, and WDR4-R170L homozygous mutation causes microcephalic primordial dwarfism." (PMID 39255038, 2024). "Recent studies have demonstrated that deficiencies in METTL1 or WDR4 abolish tRNA m7G modifications, leading to various pathological conditions, including impaired self-renewal and differentiation of embryonic stem cells, microcephalic primordial dwarfism, and Galloway-Mowat syndrome." (PMID 41292047, 2025).
Alzheimer disease (3 papers, 2023 to 2024). A progressive, neurodegenerative disease characterized by loss of function and death of nerve cells in several areas of the brain leading to loss of cognitive function such as memory and language. "Reduced levels of m7G modification on Sptbn2 mRNA due to METTL1 deficiency inhibit stability and translation, leading to impaired hippocampal neurogenesis and spatial memory in adult mice, ultimately contributing to Alzheimer's disease(AD)." (PMID 39155349, 2024). "Recently, METTL1 and its mediated m7G modifications have been found to play an essential role in neurodegenerative diseases, including Alzheimer’s disease, and in the malignant progression of tumors." (PMID 37599359, 2023). "Collectively, our data indicate Mettl1 as a novel anti-Alzheimer disease target." (PMID 37779199, 2023).
breast invasive carcinoma (3 papers, 2021 to 2025). "Several studies have revealed upregulated expression of METTL1 in other tumors, including invasive breast carcinoma (BRCA), kidney renal clear cell carcinoma (KIRC), prostate adenocarcinoma, rectal carcinoma, and uterine corpus endometrial carcinoma." (PMID 35590385, 2022).
cervical cancer (3 papers, 2014 to 2022). A primary or metastatic malignant neoplasm involving the cervix. "Notably, METTL1 also determined sensitivity of cervical cancer cells to 5-fluorouracil (5-FU), however, it is still unclear whether METTL1 participated in the regulation of chemoresistance of CC cells to Cisplatin." (PMID 31866582, 2019). "We studied NSUN2 and METTL1, the human orthologs of Trm4 and Trm8 in yeast, and demonstrated that these RTD-related tRNA modifying enzymes are involved in 5-FU sensitivity in cervical cancer HeLa cells." (PMID 25233213, 2014). "METTL1 is related to the sensitivity of chemotherapy in various cancers: overexpression of METTL1 increases the sensitivity of CC to cisplatin, while stable knockdown of METTL1 can relieve resistance to cisplatin and docetaxel in NPC and 5-fluorouracil in cervical cancer." (PMID 35590385, 2022).
multiple sclerosis (3 papers, 2022 to 2023). A progressive autoimmune disorder affecting the central nervous system resulting in demyelination. "The other study, a GWAS performed by the Australian and New Zealand Multiple Sclerosis Genetics Consortium, identified the SNP (rs703842) positioned at the 3′ untranslated region (3′ UTR) of the METTL1 gene as a multiple sclerosis susceptibility loci." (PMID 36733406, 2023). "A GWAS conducted by the Australian and New Zealand Multiple Sclerosis Genetics Consortium discovered that rs703842 positioned at the 3′ untranslated region (3′ UTR) of the METTL1 gene was associated with the risk of multiple sclerosis." (PMID 35986847, 2022). "Moreover, our study aligns with previous evidence demonstrating the association between METTL1 dysfunction and chronic immune conditions in humans, such as psoriasis and multiple sclerosis." (PMID 37516825, 2023).